LINC01890 (long independently transcribed non-coding RNA 1890)
Gene: Long non-coding RNA gene on chromosome 2 (68,822,855 to 68,845,122, reverse strand). Ensembl gene ENSG00000228329.
Diseases named in the same sentence as LINC01890 in open-access papers:
LINC01890 is named in the same sentence as 1 disease in open-access papers, as found by Europe PMC text mining. Sharing a sentence is not in itself a finding about the gene and the disease.
LINC01890 shares sentences with these, for which no sentence is quoted: infection (1 paper).